IL15 (interleukin 15)
Diseases named in the same sentence as IL15 in open-access papers (continued):
Sharing a sentence is not in itself a finding about the gene and the disease.
cancer (continued). "Using this method, we prepared a BacMam-based IL-15:IL-15Rα-secreting cell-based cancer vaccine which triggered a robust antitumor immune response in mice and, of particular note, induced cytotoxic CD8+ T cell activation." (PMID 34439192, 2021). "Other cytokines belonging to the γ-chain family exert similar effects and can be used for cancer treatment, either alone or in combination with IL-15." (PMID 33671252, 2021). "Escherichia coli-derived single-chain IL-15 was tested in the first in-human trial in cancer patients." (PMID 33671252, 2021). "Extensive studies in murine preclinical models have demonstrated the efficacy of monomeric or heterodimeric IL-15 to treat cancers." (PMID 34799399, 2021). "Collectively, we demonstrate a vaccine platform consisting of BacMam virus-infected B16F10 or CT26 cancer cells that secrete IL-15:IL-15Rα." (PMID 34439192, 2021). "The TriKE constructs were further designed to contain a human IL-15 crosslinker that prolonged in vivo persistence of adoptively transferred human NK cells and improved anti-cancer activity in a xenogeneic AML mouse model based on the AML cell line HL-60." (PMID 34372571, 2021). "At 72 h, only 19% of the B16F10 cells or 44% of the CT26 cells showed a detectable IL-15GFP signal, but the expression levels of IL-15RαGFP alone or codelivery of IL-15 + IL-15RαGFP (IL-15:IL-15RαGFP) were higher than that of IL-15GFP in both cancer cells." (PMID 34439192, 2021). "Interleukin-15 (IL-15) is a cytokine previously suggested as a potential immunotherapy for cancer treatment." (PMID 34778376, 2021). "Our results show that the combination of IL-15 with higher doses of the ADU-S100 analog led to a significant increase in cancer cell death when compared to the presence of IL-15 or ADU-S100 alone or PBS with PC3 and LNCaP cell lines." (PMID 33777767, 2021). "Additional anti-cancer effects were also observed when IL-15 was delivered together with anti-CD40 agonist antibodies in TRAMP-C2 prostatic tumor-bearing mice." (PMID 33671252, 2021). "As one of the most promising immunotherapy drug candidates for cancer treatment, IL-15 was initially found to mediate immunostimulatory functions similar to IL-2, but it has unique properties." (PMID 34107983, 2021). "IL-15 belongs to the IL-2 cytokine family; however, in a previous study, IL-15 was shown to have a wider range of therapeutic effects with fewer side effect compared to those of IL-2, making IL-15 a good candidate for cancer treatment." (PMID 33912464, 2021). "During the last two decades, several attempts to enhance NK cell functions as a therapy for the treatment of AML or other cancers have been tested including the stimulation in vitro or in vivo by γc cytokines (IL-2, IL-15, IL-21, etc.)." (PMID 34975835, 2021). "Such combination of PD-1/PD-L1 blockade and an IL-15 agonist has shown promise against cancer in vitro." (PMID 34319980, 2021). "For the codelivery of the IL-15 and IL-15RαGFP genes, the cancer cells were infected with a mixture of IL-15 BV and IL-15RαGFP BV." (PMID 34439192, 2021). "Many studies have elucidated IL-15 synthesis, regulation and biological function and explored its therapeutic efficacy in preclinical cancer models." (PMID 33671252, 2021). "The non-redundant role of IL-15 in stimulating the cytotoxic activity of immune cells has supported the clinical development of IL-15 for cancer immunotherapy." (PMID 33671252, 2021). "Feeder cells consisting of K562 expressing 4-1BBL and membrane-bound IL-15 have been used to expand NK cells for adoptive cell therapy for cancer, inducing upregulation of TRAIL, NKp44 and 4-1BB." (PMID 34244816, 2021). "Many studies have attempted to exploit the antitumor potential of IL-15 as an immunotherapeutic agent for the treatment of various types of cancer and used a number of different approaches." (PMID 34439192, 2021).
cancer (continued). "IL-15 expressed on colon epithelial cells and cancer cells can promote the growth of cancer cells, while its stimulation on NK cells has an antitumor effect." (PMID 32929618, 2021). "A similar experiment using IL-15:IL-15Rα-CT26-OVA also showed significantly reduced cancer growth compared to the control groups." (PMID 34439192, 2021). "Given the more favorable immunologic profile of IL-15, we and others have explored its potential as an immunostimulatory cytokine for the treatment of cancer." (PMID 34799399, 2021). "In this study, we introduced a new gene delivery strategy using BV to transfer and express the IL-15 and IL-15Rα genes in murine cancer cells as well as to facilitate the intracellular assembly of proteins encoded by those genes." (PMID 34439192, 2021). "The development of soluble IL-15 superagonist, greatly augmented the potency of the cytokine as a cancer immunotherapeutic agent." (PMID 33679747, 2021). "Cancer cell death in the presence of either IL-15 alone or IL-15 in combination with ADU-S100 analog was observed, but to a less extent than: IL-15-pre-incubated PBMCs resulted in 5 and 12% of LNCaP and PC3 cell death, respectively." (PMID 33777767, 2021). "Various IL-15 agonist complexes have been developed to maximize the biological activity and half-life of IL-15 to improve its immunotherapeutic potential for the treatment of chronic diseases such as cancer and HIV." (PMID 34578331, 2021). "Several viral vector-based systems including lentivirus and adenovirus have been used to deliver the IL-15 and/or IL-15Rα gene to cell-based cancer vaccines." (PMID 34439192, 2021). "In conclusion, this study focuses on a unique platform technology, incorporating IL-15 as a bispecific antibody cross-linker, thus driving NK-cell-mediated targeting of cancer." (PMID 34439149, 2021). "Here, we investigated the potential of the BacMam virus, a modified baculovirus for gene delivery into mammalian cells, as a novel multigene delivery system to generate a cell-based cancer vaccine secreting the self-assembling IL-15:IL-15Rα complex." (PMID 34439192, 2021). "During the past years, IL-15 has been considered one of the most promising cytokines in the treatment of cancer due to its ability to enhance the anti-tumoral response of CD8+ T and natural killer (NK) cells in pre-clinical studies." (PMID 34778376, 2021). "Both lentivirus and adenovirus systems have been used to make IL-15:IL-15Rα cell-based cancer vaccines for immunotherapy." (PMID 34439192, 2021). "Given these advantages, IL-15 has been used as a monotherapy or add-on strategy for cancer treatment." (PMID 33668573, 2021). "IL-15 demonstrated efficacy in murine models of cancer whilst studies in Macaques have demonstrated large increases in Tem CD8+ T-cell numbers, providing a rationale for its use as an alternative to IL-2." (PMID 34960140, 2021). "Immunization with BacMam-based IL-15:IL-15Rα-secreting cancer cells successfully raised memory immune responses against solid tumors in mice." (PMID 34439192, 2021). "Accordingly, the adoptive transfer of heterologous NK cells showed the killing of both differentiated and undifferentiated cancer cells upon activation with IL-2 and IL-15 in various cancer models." (PMID 34572009, 2021). "In the context of exercise and cancer immunology, interleukin (IL)‐15 and IL‐6 have been studied extensively and modulate the innate and adaptive immune system." (PMID 32478975, 2021). "The requirement of cancer cells in the additive killing effects of ADU-S100 analog/IL-15 was demonstrated as we saw a diminished killing when STING and IL-15 was preincubated with PBMCs alone before the 48 h co-culture." (PMID 33777767, 2021). "In conclusion, N-803 is a promising IL-15-based compound to improve NK cell-based cancer immunotherapy." (PMID 33140189, 2021).
cancer (continued). "Regarding myokines, we assessed irisin, OSM, osteonectin, IL-6, IL-15, and IL-7 on account of evidence supporting the utility of these myokines in the context of cancer prevention and control." (PMID 33555464, 2021). "To date, there are several recombinant IL-15 agonists based on configurational modifications that are being pursued in the treatment of cancer, such as ALT-803, which are mainly produced from mammalian cells." (PMID 34107983, 2021). "The purpose of this study was to investigate the in vivo therapeutic efficacy of CD44-targted NIR-PIT and IL-15 treatment in syngeneic mouse models of cancer compared to either therapy alone." (PMID 32927646, 2020). "The pivotal roles of IL-2 and IL-15 in activating CD8+T cells lead to the wide usage of these two cytokines in cancer immunotherapy." (PMID 33266177, 2020). "In arms ii-v of this trial, the CAR-NK cells have been engineered to secrete IL-15 based on studies showing improved in vivo persistence of CAR-NK cells in cancer patients." (PMID 32655581, 2020). "Immunotherapy has improved the treatment outcomes in patients with cancer, and continuous efforts are devoted to exploiting the therapeutic potential of IL-2 and IL-15 based on their ability to expand and activate cytolytic lymphocytes in vivo." (PMID 33266177, 2020). "Despite their dramatic augmentation of NK cells and CD8 T cells, all IL-15 preparations administered as monotherapy in solid tumor patients with cancer have been ineffective probably due to counter-regulatory immunologic processes." (PMID 32508818, 2020). "In translation, a phase I trial was initiated involving IL-15 (rhIL-15), nivolumab and ipilimumab in patients with malignancy (NCT03388632)." (PMID 32508818, 2020). "IL-15 regulates NK and memory T cell homeostasis and is therefore being explored for clinical immunotherapy of chronic diseases like cancer and HIV." (PMID 32163523, 2020). "Emerging knowledge of the two type I cytokine family members IL-2 and IL-15 has led to critical therapeutic implications for cancer treatment." (PMID 33266177, 2020). "Preclinical cancer studies support the use of IL-15 to promote the development of antitumor responses by increasing intratumoral lymphocyte infiltration, favoring effector over regulatory cells, and by promoting DC-T cell interactions." (PMID 32461349, 2020). "The human IL-15 superagonist N-803 (formerly ALT-803) is a promising anti-cancer biologic with potent immunostimulatory properties that has been extended into the field of HIV as a potential “shock and kill” therapeutic for HIV cure." (PMID 32163523, 2020). "IL-15 is considered superior to IL-2 for cancer immunotherapy due to its strong bioactivity in improving CD8+ T and natural killer (NK) cell survival, proliferation and cytotoxic function." (PMID 33628206, 2020). "Because of its ability to potently induce NK and T cell proliferation in cancer models, N-803, a novel IL-15 superagonist, is now a promising candidate for targeting and eradicating the HIV reservoir." (PMID 32163523, 2020). "IL-15 has emerged as a potential immunotherapeutic candidate for cancer treatment, especially in combination with other agents." (PMID 32605193, 2020). "IL-15 is another cytokine that signals through the IL-2Rβγ, and it is being tested in clinical trials for cancer immunotherapy, including patients with metastatic RCC." (PMID 32013092, 2020). "Here, we summarize the current knowledge about the biology and function of IL-2, IL-15 and their receptor systems, with further discussion on clinical applications of these two cytokines for cancer treatment." (PMID 33266177, 2020). "IL-15 has emerged as an alternative to IL-2 in cancer treatment, for its potent effects on cytolytic NK and T cells without inducing suppressive Treg cells." (PMID 33266177, 2020). "Discerning the roles of IL-2 and IL-15 in the regulation of antitumor immune responses is critical for the development of immunotherapeutic approaches against cancer." (PMID 33266177, 2020).
cancer (continued). "The ability of IL-15 to regulate and stimulate both innate and adaptive immune cells makes it an attractive anti-cancer agent." (PMID 33096755, 2020). "This study focuses on a unique biologic platform technology, incorporating IL-15 as a bispecific antibody cross-linker, to drive NK-cell-mediated targeting of a broad spectrum of cancers." (PMID 32961861, 2020). "Here, we discuss recent clinical and preclinical advances of IL-2- or IL-15-based immunotherapy in cancer patients." (PMID 33266177, 2020). "This clearly demonstrated a superiority of IL-2/IL-15-expanded cells over IL-2-expanded cells in terms of cytotoxicity against a variety of cancer cells." (PMID 32983105, 2020). "The first clinical trial with single-chain IL-15 (scIL-15) in cancer patients exhibited high dose-dependent toxicity." (PMID 32013092, 2020). "While IL-2 is considered a prototype for γ-chain cytokines and is the quintessential growth factor for T cells, we have opted to use IL-15 instead to combine with IL-12 as a better candidate for cancer immunotherapy for several reasons." (PMID 33182232, 2020). "These are PTEN signaling, Myc mediated apoptosis signaling, molecular mechanisms of cancer, IL-15 signaling, and PEDF signaling." (PMID 31355136, 2019). "Preclinical experiments with several murine cancer models showed very promising antitumor effects of granulocyte–macrophage colony-stimulating factor (GM-CSF), IL-2, IL-12, IL-15, and IL-21." (PMID 31083515, 2019). "IL-15 administration markedly affected the function and proliferation NK cells in these cancer patients." (PMID 30601063, 2019). "Interleukin-15 is currently being investigated as an immunotherapeutic agent for the treatment of cancer [NCT01021059, NCT01727076, NCT01885897]." (PMID 31623390, 2019). "More data is necessary to evaluate the effectivity of IL-15 or IL-15 analogs in cancer treatment in combination with RT." (PMID 31179236, 2019). "In order to find an explanation for the observed differences in survival and immunity, we examined the cytokine and chemokine profile in serum of mice injected with IL-15-secreting cancer cells, shedding light on the systemic nature of these molecules." (PMID 31856922, 2019). "A lot of studies have suggested that IL-18 shows anti-cancer effects in combination with other cytokines including IL-12 and IL-15 as results of inducing T cell proliferation and NK cell activation in vitro." (PMID 31731729, 2019). "We also demonstrated here that IL-15/IL-18/IL-27-stimulated NK cells retained high perforin expression and underwent some target-dependent degranulation and that target cancer cells experienced caspase-dependent apoptosis." (PMID 31277710, 2019). "Most of the validated genes, such as IL15, ITGAM, PDK4, and IRX5, have been implicated in AML progression and/or as survival predictors in several types of cancers." (PMID 31740623, 2019). "The use of the cytokine IL-15 to boost the immune system against cancer cells has significant potential in cancer immunotherapy." (PMID 30601063, 2019). "Interleukin-15 (IL15) is one of the most important cytokines currently being considered for cancer therapy applications." (PMID 31348785, 2019). "We found more enriched terms linked to cancer, such as “mTOR signaling pathway”, “Jak-STAT signaling pathway”, “hematopoietic stem cell differentiation” and “response to interleukin-15” (hematopoietic growth factor." (PMID 31142264, 2019). "ALT-803 is an interleukin-15 superagonist complex that enhances ADCC against human carcinoma cells in vitro and exerts an antitumor activity in murine, rat, and human carcinomas in vivo." (PMID 30601063, 2019). "The addition of a high concentration of exogenous ADO did not lead to a significant reduction in cytolysis against A549 cancer cells by cytokine-stimulated NK cells when primed with either IL-2 or a combination of IL-12 and IL-15." (PMID 30425720, 2018).
cancer (continued). "In agreement with the existing evidence, treating whole blood of patients with cancer with IL-2, IL-15 and IL-21 markedly improved the antigen-specific IFNγ response regardless of existing immunosuppression, thereby suggesting clinical applicability." (PMID 29970101, 2018). "IL-15 is a cytokine that activates and provides survival benefit to T and NK cells and has potential as an immunotherapeutic agent for the treatment of cancer." (PMID 30400822, 2018). "This renovates the prospect of using IL-15 as a cancer immunotherapeutic drug and combining it with other immuno-oncological agents." (PMID 30294328, 2018). "MART-1-targeted and PRAME-targeted CTLs elicit specific cytotoxicity against human cancer cells expressing their respective antigen target, and Deep IL-15 augments this activity." (PMID 30400835, 2018). "Our data provide evidence of a major contribution of IL-15 to CIML NK cell-mediated cytotoxicity against K562 cancer cells." (PMID 29713323, 2018). "Currently several clinical trials are investigating IL-15 for cancer treatment of which one investigates ALT-803 in combination with gemcitabine and nab-Paclitaxel in PDAC (NCT02559674)." (PMID 28915646, 2017). "Gene expression analysis identified Cancer, Cell Death, Immune Response and Lipid Metabolism as the major diseases and functions altered in tumors treated with IL-15." (PMID 28379958, 2017). "Other studies also show the effect of IL-15 on cancer initiation and progression in immunodeficient mice." (PMID 29255466, 2017). "Other cytokines have been proposed for cancer treatment, and, in the last years, IL-15 has emerged as a potential immunotherapeutic candidate." (PMID 28824651, 2017). "Herewith, IL-15 DCs represent a promising cancer vaccine, stimulating both innate and adaptive antitumor immune effector cells." (PMID 28099143, 2017). "IL-15 treatment deregulated the expression of 917 genes classified in 4 broad diseases and functions: cancer, cell death, immune response and lipid metabolism." (PMID 28379958, 2017). "These factors support the role of IL-15 for cancer immunotherapy, boosting both innate and adaptive immunity against tumors." (PMID 28824651, 2017). "Conversely, harnessing the powerful immunostimulatory effects of IL15 has shown potential as a cancer immunotherapy agent and clinical phase I trials are currently underway (reviewed in18)." (PMID 26822794, 2016). "Nevertheless, NK cells treated with IL-18 in combination with IL-12 or triple therapy with IL-12, IL-15 and IL-18 resulted in strongly augmented NK cell degranulation and proliferation in cancer studies." (PMID 27821119, 2016). "By linking scFv-related targeting of carcinoma and CSCs with a sustaining IL-15 signal, our new construct shows great promise to target cancer and CSCs." (PMID 27650544, 2016). "The common gamma-chain cytokine interleukin-15 (IL-15) is considered as one of the most promising cytokines for cancer immunotherapy." (PMID 26625316, 2016). "This has now been confirmed in the first-in-human trial of recombinant IL-15, whereby IL-15 administration in cancer patients induced both γδ T cell proliferation and activation." (PMID 27686372, 2016). "IL-15 effects represent beneficial characteristics in cancer treatment, which can be specifically delivered to the effector cells with our TetraKE." (PMID 27650544, 2016). "Due to the ability of IL-15 to stimulate both the innate and the adaptive arm of the immune system, including in the context of antitumor immunity, IL-15 was labeled as the immunotherapeutic drug with the greatest potential for broad usage in cancer therapy." (PMID 26675759, 2015). "Most in vivo studies investigating the effects of IL-15 have used subcutaneous engrafted or lung metastasis cancer models." (PMID 25879689, 2015). "Previous studies showed that exogenous treatment or overexpression of IL-15 promotes myoblast differentiation and muscle hypertrophy and ameliorates muscle wasting in cancer cachexia." (PMID 26417430, 2015).